LINC00944 (long independently transcribed non-coding RNA 944)
Synonyms: DMDRMR; LOC100996671
Gene: Long non-coding RNA gene on chromosome 12 (126,599,954 to 126,772,519, reverse strand). Ensembl gene ENSG00000256128.
Diseases named in the same sentence as LINC00944 in open-access papers:
LINC00944 is named in the same sentence as 16 diseases in open-access papers, as found by Europe PMC text mining. Sharing a sentence is not in itself a finding about the gene and the disease. The quoted sentences say what the papers report.
breast carcinoma (5 papers, 2021 to 2025). "In breast cancer, LINC00944 expression is linked to ADAR1 levels and immune signaling pathways, including tumor-infiltrating T lymphocytes." (PMID 39941858, 2025). "In this study, we focused on LINC00944, which has been linked to cancer progression and the presence of immune infiltrating cells in several types of cancer, including RCC, breast cancer, lung cancer, and gastric cancer." (PMID 39941858, 2025). "Clinicopathological and experimental evidence indicates that LINC00944 plays a role as an oncogene in renal cell carcinoma (RCC) and has prognostic value in breast cancer." (PMID 36168326, 2022). "Moreover, de Santiagoe revealed that LINC00944 can be regulated and affected by ADAR1 in breast cancer cells, and this lncRNA was strongly related to the immune signal pathway." (PMID 34378851, 2021).
renal cell carcinoma (5 papers, 2021 to 2024). "Overexpression of LINC00944 promotes tumor occurrence and is significantly associated with the staging and poor prognosis of renal cell carcinoma." (PMID 39469643, 2024). "Previously, LINC00944 has been validated as a cancer-associated lncRNA28; it is highly expressed in renal cell carcinoma tissues, and its high expression is associated with tumour stage, tumour-infiltrating T lymphocytes, and pro-apoptotic markers." (PMID 37029263, 2023). "Regarding renal cell cancer, LINC00944 contributes to its development by enhancing cancer cell proliferation and migration." (PMID 39684278, 2024). "In our study, we identified the expression of lncRNA LINC00944 is significantly elevated in renal cell carcinoma (RCC) tissues and cell lines and high LINC00944 expression is significantly correlated with the tumor stage and prognosis of RCC." (PMID 34291088, 2021).
gastric cancer (2 papers, 2022 to 2025). A primary or metastatic malignant neoplasm involving the stomach. "Elevated LINC00944 expression is also associated with gastric cancer and lung cancer, such as lung squamous cell carcinoma and lung adenocarcinoma, and is used in prognostic risk score assessments and survival prediction models." (PMID 39941858, 2025).
colon cancer (1 paper, 2020). "These included lncRNA LINC00944, which has been shown to participate in the process of liver metastasis in colorectal cancer, and lncRNA LINC00460, hypo-methylation of which can promote colon cancer and represents a potential biomarker." (PMID 33329694, 2020).
head and neck squamous cell carcinoma (1 paper, 2025). A squamous cell carcinoma that arises from any of the following anatomic sites: lip and oral cavity, nasal cavity, paranasal sinuses, pharynx, larynx, and salivary glands. "The LINC00944 expression was analyzed from a database of head and neck squamous cell carcinoma (HNSCC) tissues, and its expression in EBV-positive and EBV-negative OSCC cell lines was examined via qRT-PCR." (PMID 39941858, 2025). "Key findings indicated that LINC00944 was upregulated in head and neck squamous cell carcinoma (HNSCC) tissues and Epstein–Barr virus (EBV)-positive oral cancer cell lines, suggesting its involvement in carcinogenesis and a potential influence of EBV infection on its gene expression." (PMID 39941858, 2025).
oral cancer (1 paper, 2025). "Upregulation of LINC00944 in EBV-associated OSCC contributes to oral cancer progression by promoting migration and invasion through one of its functions as ceRNA, which targets specific miRNAs that regulate proteins in the TNFα/NF-κB signaling pathway." (PMID 39941858, 2025). "LINC00944 is associated with various cancers and immune cells, but its role in oral cancer remains underexplored." (PMID 39941858, 2025). "However, LINC00944’s association with and impact on the carcinogenesis and tumor microenvironment in oral cancer remains unexplored." (PMID 39941858, 2025). "Our investigation revealed that LINC00944 can be secreted from oral cancer cells that overexpress LINC00944." (PMID 39941858, 2025). "Our findings indicated that the overexpression of LINC00944 promotes metastasis in oral cancer cells by enhancing both migration and invasion abilities." (PMID 39941858, 2025). "In our study, we found that elevated levels of LINC00944 promote the progression of oral cancer by increasing metastatic abilities." (PMID 39941858, 2025). "The study concludes that LINC00944 may play an essential role in oral cancer metastasis and progression and could be suggested as a potential therapeutic target for oral cancer." (PMID 39941858, 2025). "Collectively, these results suggest that LINC00944, secreted by oral cancer cells, may promote an M1-like macrophage phenotype." (PMID 39941858, 2025). "LINC00944 promoted oral cancer cell progression by enhancing migration, invasion, and metastasis." (PMID 39941858, 2025). "This suggested that EBV infection may impact the expression of LINC00944 in oral cancer cells." (PMID 39941858, 2025). "Furthermore, we investigated whether the predicted candidate miRNAs, which are downregulated in oral cancer and are predicted to be targets of LINC00944, could regulate key mRNAs involved in the TNF-α/NF-κB signaling pathway." (PMID 39941858, 2025). "We overexpressed LINC00944 in SCC25 and ORL-48T oral cancer cell lines and evaluated its impact on migration and invasion ability using wound healing and transwell experiments." (PMID 39941858, 2025).
oral squamous cell carcinoma (1 paper, 2025). "In this study, we overexpressed LINC00944 in oral squamous cell carcinoma cell lines including SCC25 and ORL-48T cells." (PMID 39941858, 2025).
renal carcinoma (1 paper, 2021). A carcinoma arising from the epithelium of the renal parenchyma or the renal pelvis. "Cell function experiments have shown that downregulation of LINC00944 can reduce the proliferation and metastasis of renal cancer cells." (PMID 34291088, 2021). "In this study, we searched renal cancer–related datasets through the TCGA database and screened lncRNAs, and we found that lncRNA LINC00944 was significantly upregulated in renal cancer tissues." (PMID 34291088, 2021). "In this study, through the screening and analysis of multiple databases, we screened the lncRNA LINC00944 with obvious differential expression in renal cancer tissues and paracancerous tissues and verified the high expression of LINC00944 in renal cancer tissues." (PMID 34291088, 2021). "Therefore, LINC00944 may be closely related to the proliferation and metastasis of renal cancer and play a role in promoting tumor progression." (PMID 34291088, 2021). "LINC00944 may become one of the effective therapeutic targets for renal cancer." (PMID 34291088, 2021).
tumor (10 papers, 2021 to 2025). "LINC00944 was mainly expressed in epithelial and T cells, suggesting a strong association between LINC00944 and immune cell infiltration apart from its significantly high expression in ccRCC tumor cells." (PMID 37415739, 2023). "In conclusion, EBV-induced LINC00944 contributes to OSCC progression by enhancing tumor cell migration, invasion, and macrophage differentiation, potentially regulating these processes through NFKB1 and RELA." (PMID 39941858, 2025). "Further evaluation of the TCGA-BRCA cohort revealed that LINC00944 expression was positively correlated with tumour-infiltrating T lymphocytes and proapoptotic markers." (PMID 36936957, 2023). "LINC00944 expression was positively correlated to tumor infiltrating T lymphocytes, the age at diagnosis, tumor size, and poor prognosis." (PMID 35898396, 2022). "Therefore, this study aimed to investigate the role of LINC00944 in oral carcinogenesis and its impact on the tumor microenvironment." (PMID 39941858, 2025). "In RCC, elevated LINC00944 levels correlate with advanced tumor stages and poorer prognosis." (PMID 39941858, 2025). "Furthermore, the results showed that the expression of LINC00944 correlated with age at diagnosis, tumour size, and estrogen and progesterone receptor expression." (PMID 36936957, 2023). "This study investigated the role of EBV-induced LINC00944 in OSCC and its impact on the tumor microenvironment." (PMID 39941858, 2025). "Previous studies of LINC00944 functions showed that the increasing level of LINC00944 promotes cancer progression in RCC, while a lower level of it correlates with the increasing tumor size." (PMID 39941858, 2025). "LINC00944, LINC02611, PRKAR1B-AS1, LINC02328 and LINC02100 were expressed at higher levels in ccRCC tumor tissues compared to that in normal tissues, which was consistent with the results of the TCGA-ccRCC cohort." (PMID 37415739, 2023). "RT–qPCR results showed that LINC00924, LINC00944, and LINC00865 were highly expressed in tumour tissues, while LINC00702 and ZFAS1 were expressed at low levels in tumour tissues." (PMID 36936957, 2023). "The expression levels of LINC00460, LINC00944, LINC01550, and EPB41L4A-DT differed across the four stages, suggesting that four FRlncRNAs were closely related to the tumor stage." (PMID 35350243, 2022). "The expression levels of four FRlncRNAs were verified by qRT-PCR from twenty ccRCC patients, which found that LINC01550 and EPB41L4A-DT in tumor tissues were downregulated, while LINC00460 and LINC00944 were upregulated." (PMID 35350243, 2022).
cancer (7 papers, 2020 to 2025). A tumor composed of atypical neoplastic, often pleomorphic cells that invade other tissues. "Overall, these findings suggest that LINC00944 may play a role in targeting miRNAs associated with various cancer-related pathways, key signaling cascades, and mechanisms driving cancer progression." (PMID 39941858, 2025). "Currently, four FRlncRNAs (LINC01615, LINC01550, EPB41L4A-DT, and LINC00944) have been reported to be related to cancer development." (PMID 35350243, 2022). "Based on the relative ranks of lincRNAs, we identified several cancer-related lincRNAs, such as LINC00944 and SMIM2538,39." (PMID 32081859, 2020). "Overexpression of LINC00944 in OSCC cell lines enhanced cancer cell migration and invasion." (PMID 39941858, 2025). "This alteration in LINC00944 expression in cancer tissues could suggest its potential involvement in carcinogenesis." (PMID 39941858, 2025). "This study examined the role of LINC00944 in OSCC and its association with cancer progression." (PMID 39941858, 2025). "Subsequent studies on LINC00944 and LINC02611 revealed their high expression in ccRCC and significant correlation with cancer cell migration and invasion." (PMID 37415739, 2023).
LINC00944 also shares sentences with these, for which no sentence is quoted: clear cell renal cell carcinoma (2 papers); colorectal cancer (1); esophageal squamous cell carcinoma (1); lung carcinoma (1); melanoma (1); Sepsis (1).